STAT5B (signal transducer and activator of transcription 5B)
Diseases named in the same sentence as STAT5B in open-access papers (continued):
Sharing a sentence is not in itself a finding about the gene and the disease.
Immunodeficiency (30 papers, 2010 to 2025). Failure of the immune system to protect the body adequately from infection, due to the absence or insufficiency of some component process or substance. "Patients with homozygous LOF STAT5B mutations exhibit a combination of severe growth hormone insensitivity and significant immunodeficiency." (PMID 41438753, 2025). "Similar biochemical and growth profiles are observed in patients with biallelic signal transducer and activator of transcription 5B (STAT5B) mutations, though these cases are often complicated by immune dysfunction and elevated prolactin levels." (PMID 40723048, 2025). "Alternatively, STAT5B is known to mediate growth hormone signaling and mutations in the STAT5B gene have been associated with stunted growth, autoimmunity and immunodeficiency." (PMID 39763651, 2024). "Congenital inactivating human STAT5B mutations, associated with severe growth failure and immune deficiencies, have been identified in several Laron syndrome patients." (PMID 39803507, 2024). "A recent human study showed that a STAT5B gene mutation resulted in reduced serum IGF1 in most patients with immunodeficiency growth hormone insensitivity, accompanied by growth retardation and poor growth hormone therapy." (PMID 37235421, 2023). "In line with the role of STAT5B as mediator of IL-2 signaling, these patients undergo recurrent infections due to immunodeficiency caused by impairment in T, regulatory T (Treg), and NK cell differentiation and activation." (PMID 31690038, 2019). "Severe growth hormone insensitivity syndrome (GHIS) with immunodeficiency is caused by autosomal recessive mutations in STAT5B." (PMID 29844444, 2018). "STAT5B deficiency is linked to immunological aberrations such as allergic diseases, immunodeficiencies, autoimmunities, as well as cancers." (PMID 29268715, 2017). "Homozygous STAT5B mutations causing growth hormone insensitivitywith immune dysfunction were described in 10 patients since 2003, including twoBrazilian brothers from the south of Brazil." (PMID 28590503, 2017). "As mentioned in the Introduction section, chronic lung disease and immune dysfunction appear to be common among patients that are deficient in STAT5B." (PMID 23565285, 2013). "Differently, severe immunodeficiency is observed in another form of GH insensitivity due to a mutation in the signal transducer and activator of transcription 5B (STAT5B) gene, with reduced IGF-1 production, impaired response to infections and high production of prolactin (PRL)." (PMID 37426675, 2023). "STAT5B deficiency can result in immunodeficiency and growth failure." (PMID 33155364, 2021). "Interestingly, in mouse models, severe growth restriction and immune deficiency were observed only in the knock-out of both the Stat5b and Stat5a genes, but expression of normal Stat5a/b as low as ~10% significantly reduced the severity of immunodeficiencies." (PMID 29844444, 2018). "Also, NK-LGLL may affect the kidney through other multiple mechanisms that include direct infiltration, disturbance of immunity, paraneoplastic syndrome, viral infection such as EBV, and immune disorders caused by STAT5B mutation." (PMID 40629603, 2025). "Promoter hypermethylation of STAT5A, STAT5B, or SOCS1/3 genes has been implicated in the silencing of pathway modulators in various cancers and immune disorders." (PMID 41438753, 2025). "Some immunodeficiency diseases, such as adenosine deaminase (ADA) deficiency, DiGeorge syndrome, and STAT5b deficiency manifested as the abnormal development of cartilage." (PMID 36684670, 2023). "In human STAT5b, the naturally occurring amino acid substitution F646S, the second reported mutation, is associated with severe IGF-I deficiently, immune dysfunction, and pulmonary disease." (PMID 26717567, 2015). "STAT5B SH2 mutations associated with the growth hormone insensitivity (GHI) syndrome include A630P, K632N, F646S and V669F result in postnatal growth failure and, in some cases, immune deficiency." (PMID 38903072, 2024).
Immunodeficiency (continued). "Loss-of-function (LOF) mutations in STAT5B led to human primary immune deficiencies affecting NK cells —so far not reported for STAT5A." (PMID 31690038, 2019). "Our patients lacked the severe immune deficiency and pathological autoimmunity typically associated with total STAT5B deficiency." (PMID 29844444, 2018). "In addition to LOF variants, the STAT5B deficiency can also result from the autosomal dominant form of STAT5B, causing stunted growth and eczema, but it does not lead to severe immunodeficiency." (PMID 40666020, 2025).
lymphoma (24 papers, 2013 to 2025). A malignant (clonal) proliferation of B- lymphocytes or T- lymphocytes which involves the lymph nodes, bone marrow and/or extranodal sites. "Although our meta-analysis highlights the predominantly tumor-suppressive associations of STAT5B across epithelial cancers and lymphomas, it is equally important to recognize its established oncogenic functions in specific hematologic malignancies." (PMID 41301421, 2025). "Our data suggest that this oncogenic driver of T cell leukemia/lymphoma should be thought of as a de novo transcription factor with a set of cancer-associated target genes that is qualitatively different from wild-type STAT5B." (PMID 38658806, 2024). "Mutated STAT3 is mainly associated with large granular lymphocytic T-cell leukemia, whereas mutated STAT5B is associated with T-cell prolymphocytic leukemia, T-cell acute lymphoblastic leukemia and γδ T-cell-derived lymphomas." (PMID 31817042, 2019). "The discoveries of STAT5B mutations in NK and T cell leukemia/lymphoma and STAT5B-deficient patients unambiguously indicate STAT5B’s particular importance." (PMID 31690038, 2019). "In addition, in the JAK–STAT pathway, we found the GG genotype of STAT3 rs744166 compared with AA and the T allele of STAT5B rs6503691 compared with C were significantly associated with lymphoma susceptibility." (PMID 37329186, 2023). "Finally, mice which expressed a transgene, i.e., a human gain-of-function mutation of STAT5B (hSTAT5B N642H) identified in leukemic patients, developed lymphomas from multiple T cell subsets." (PMID 31766350, 2019). "Such activating mutations on STAT5b have also been observed in lymphomas derived from γδ-T or NK cells with a high frequency, especially in γδ-T-cell-derived lymphomas and enteropathy-associated T-cell lymphoma type II, where STAT5b mutations were observed in more than 30% of tumor samples." (PMID 30262727, 2018). "The study of the underlying pathological context, the cytogenetical and TCR-γ clonality analyses and the search of mutations in the SH2 domain of STAT3 and STAT5b should help to distinguish LGL leukemia or other malignant lymphomas from non clonal CD8+ T-cell expansions." (PMID 24618699, 2014). "This comprehensive analysis identifies STAT5B as a multifaceted regulator of cancer biology, with predominantly tumor-suppressive characteristics across epithelial cancers and protective associations in lymphomas, but oncogenic potential in specific hematologic contexts." (PMID 41301421, 2025). "As JAK–STAT and NF‐κB pathways were involved in lymphoma, we first found that the rs744166 of STAT3 and rs6503691 of STAT5B contributed to lymphoma susceptibility under codominant, recessive, codominant, and allele models (all p < 0.05)." (PMID 37329186, 2023). "Our results showed that both IL6R (rs2228145) and STAT5B (rs6503691) significantly contributed to the Ann Arbor stages of lymphoma." (PMID 37329186, 2023). "On a genetic level, these lymphomas show frequent gains of 8q24 (including MYC gene) and recurrent mutations of STAT5b, JAK3, GNAI2, and SETD2." (PMID 37345080, 2023). "Next-generation sequencing of ENKTL and aggressive NK-cell leukemia (ANKL) has shown recurrent mutations in the JAK/STAT pathway, particularly in STAT3 and STAT5B in both lymphoma entities." (PMID 35330161, 2022). "Both proteins, STAT3 and STAT5B, are activated in virtually all of the alimentary lymphoma samples examined." (PMID 34680385, 2021). "In the ENKTCL arising in East Asia, genetic analyses have shown that activating mutations of the JAK-STAT pathway, such as in JAK3 (5–35%), STAT3 (6–27%) and STAT5B (2–6%) genes are characteristic of this lymphoma." (PMID 32759793, 2020). "Overall, strong STAT5B hyperactivity appeared to trigger B or T lymphomas when express during lymphoid cell development and to directly influence disease aggressiveness and therapeutic resistance." (PMID 31766350, 2019).
lymphoma (continued). "Approximately 13% of these F1 mice developed lymphoma by 30 weeks of age, similar to the incidence reported for Stat5b transgenic mice in the B6 background (∼12%)." (PMID 23457589, 2013). "STAT5B and STAT3 mutations are virtually exclusive in occurrence, whereas STAT5B and PIK3CD mutations potentially complement each other in creating cooperativity between PI3K and JAK-STAT signaling in maintaining proliferation pathways in HSTL lymphoma cells." (PMID 35330161, 2022). "Similarly, STAT5b mutation is frequent in gamma F-PTCL and NK-cell-derived lymphomas." (PMID 37746258, 2023). "Despite the STAT5B hyperactivation and the presence of multiple STAT5B mutations, the clinical course of CD4+ T-LGLL is indolent, and patients rarely have symptoms, differentiating it from CD8+ T-LGLL and other mature and immature CD4+ T-cell leukemias and lymphomas." (PMID 35210405, 2022). "Therefore, we hypothesized that transgenic Stat5b in the NOD genetic background may enhance lymphoma development." (PMID 23457589, 2013). "However, the molecular mechanism underlying the disease remains elusive because Stat5b phosphorylation was surprisingly not observed in these transgenic mice with or without lymphomas." (PMID 23457589, 2013). "Of note, STAT3/STAT5B mutations were absent in all non-LGL T-CLPD patients, except for an adult T-cell leukemia/lymphoma case that showed the STAT3-S614R mutation." (PMID 33255665, 2020). "Comparative studies on the molecular and cellular phenotypes for the NOD.Stat5bTg mice, which have a high lymphoma incidence, and the B6.Stat5bTg and NOD/B6 F1.Stat5bTg mice which have low incidence of lymphoma, shed new lights on the role of Stat5b and the NOD genetic background on lymphomagenesis." (PMID 23457589, 2013). "In summary, STAT3 and STAT5B, but not STAT5A, are relevant therapeutic targets in the treatment of lymphomas." (PMID 31963765, 2020).
T-LGL leukemia (20 papers, 2014 to 2025). "Activating STAT5b mutations have also been found in 55% of CD4+/CD8−/TCRαβ+ T-LGL leukemia patients but are very rare among patients with CD4−/CD8+ T-LGL leukemia or NK-LGL." (PMID 38610985, 2024). "Mutations in STAT5B are more frequently associated with T-LGL leukemia, more specifically, CD3+/CD56+ and CD4+ subsets of T-LGL leukemia." (PMID 36755813, 2022). "Activating mutations in the SH2 domain of STAT3 (Y640F, D661Y/V) and STAT5B (N642H) were also described in T-LGL leukemia which is a chronic lymphoproliferative disorder characterized by the expansion of some cytotoxic T cell or NK cell populations." (PMID 31963765, 2020). "Increased activation of this pathway results from increased cytokine signaling and somatic activating mutations in STAT3 and STAT5B, further implicating the oncogenic role of this pathway in LGL leukemia." (PMID 31947841, 2020). "STAT3 mutations have been described in 30–40% of T-LGL leukemia patients while STAT5B mutations were found in rare but typical CD4+ T-LGL leukemia cases." (PMID 31963765, 2020). "Mutated STAT5b also has been observed in some large granular lymphocytic leukemias, though in a substantially smaller number of patient tumors." (PMID 30116531, 2018). "In fact, STAT3 and STAT5b mutations represent an exclusive marker of CD8+ T-LGL leukemia and CD4+ T-LGL leukemia, respectively." (PMID 28977911, 2017). "According to a recent report showing high incidence of STAT5b mutations in CD4+ T-LGL leukemia, we evaluated also the presence of STAT5b mutations in all our cohort of study." (PMID 28977911, 2017). "Mutations in the STAT5B gene have been found in 2% of patients with LGL leukemia." (PMID 39161592, 2024). "STAT3 and STAT5B (STAT3/STAT5B) mutations are the most common mutations in T-cell large granular lymphocytic leukemia (T-LGLL) and chronic lymphoproliferative disorders of NK cells (CLPD-NK), but their clinical impact remains unknown." (PMID 33255665, 2020). "For example, amplification of STAT3 or STAT5B has been reported in T-cell large granular lymphocytic leukemia and other malignancies." (PMID 41438753, 2025). "Activating STAT5B mutations, particularly STAT5BN642H, have been identified in T-cell large granular lymphocytic leukemia and other hematologic cancers, where they drive constitutive JAK–STAT signaling and malignant proliferation." (PMID 41301421, 2025). "Along with mutations in STAT5B, mutated STAT3 leads to constitutive activation and plays a fundamental role in the pathogenesis of LGL leukemia." (PMID 36755813, 2022). "All patients exhibit constitutive STAT1 and STAT3 phosphorylation, and the occurrence of STAT5B and STAT3 somatic activating mutations are a hallmark of LGL leukemia." (PMID 31947841, 2020). "In all cases, mutations were shown to increase the transcriptional activity of both STAT3 and STAT5B proteins, but only the STAT5BN642H mutation was demonstrated to drive T-LGL leukemias in mouse models." (PMID 31963765, 2020). "This might suggest that STAT3 and STAT5b are less clearly implicated in the pathogenesis of TCRγδ+ T-LGL leukemia than CD8+TCRαβ+ T-LGL and/or NK-LGL leukemia." (PMID 28407008, 2017). "One study demonstrated that the disease course in the CD4+ T-LGL leukemia cohort is indolent, and none of the patients with STAT5b mutations appeared to require therapy during the observation period." (PMID 38610985, 2024). "There are a couple key differences to note between STAT3 and STAT5b mediated LGL leukemia." (PMID 36755813, 2022). "One is that CD4+ T-LGL leukemia is characterized only by STAT5B mutations and not STAT3 mutations." (PMID 36755813, 2022). "Interestingly, mutated STAT3 is mainly associated with large granular lymphocytic T-cell leukemia (T-LGLL), whereas mutated STAT5B is found in patients with T-cell prolymphocytic leukemia (T-PLL), T-ALL, γδ T-cell-derived lymphoma and monomorphic epitheliotropic intestinal T-cell lymphoma (MEITL)." (PMID 31817042, 2019).
T-LGL leukemia (continued). "Moreover, our results provide further evidence of the correlation between STAT5b mutations and CD4+ T-LGL leukemia, recently described in a small cohort of cases (n = 11) and here confirmed in a larger cohort of patients (n = 33) even if with a lower incidence (15.2% vs 55% reported)." (PMID 28977911, 2017). "Moreover, activating mutations in the SH2 domain of STAT5b have been identified in 2% of NK-LGL leukemia patients, who are characterized by a more aggressive and fatal clinical course, unlike typical LGL leukemia." (PMID 38610985, 2024).
Autoimmunity (19 papers, 2012 to 2025). The occurrence of an immune reaction against the organism's own cells or tissues. "Mutations in the STAT5B gene are linked to impaired protein signaling and function and are associated with stunted growth, autoimmunity and immunodeficiency." (PMID 36755813, 2022). "The impact of STAT5B activity at the maternal-fetal interface is unknown, however observations have linked aberrant activation of STAT5B to autoimmunity, the development of certain cancers, and interestingly, a syndrome of severe allergic inflammation." (PMID 39763651, 2024). "Furthermore, 75% of the patients with Wiskott-Aldrich syndrome, and 100% of the patients with STAT5b deficiency suffered from autoimmunity." (PMID 32582199, 2020). "The investigation of PPARα-independent mechanisms of PFAS toxicity also suggests suppression of STAT5B, a transcription factor activated by cytokines and involved in the immune cell development and autoimmunity." (PMID 33804855, 2021). "The frequency of autoimmunity was high among patients with RAG, WAS, STAT5b, NF-κB2, Fas, FasL, LRBA, APECED, IL-10, and C4 deficiencies." (PMID 32582199, 2020). "We screened all participants for the seven genes known to cause monogenic autoimmunity that can include diabetes (AIRE, IL2RA, FOXP3, LRBA, STAT1, STAT3, STAT5B)." (PMID 29417186, 2018). "In this review, we focused on the STAT5b pathway and the mechanisms by which defects in protein structure and or expression might result in autoimmunity." (PMID 22912632, 2012). "Furthermore, Stat5b-CA.BMDCs may also promote Treg development and their immunoregulatory function to prevent autoimmunity." (PMID 32899608, 2020). "The other nodes of the network mainly contain genes/proteins related to autoinflammatory/autoimmunity, such as JAK1, STAT3, STAT5B, IL10RA, and IL10RB, with SOCS3 as a hub." (PMID 39359477, 2024). "Another signaling pathway relevant to autoimmunity is the Jak-stat pathway that is represented in our dataset by the upregulation of STAT1 and STAT5b." (PMID 28441778, 2017). "AD STAT5b deficiency: growth-failure and eczema without immune defects; (iii) AD STAT1 GOF CMC and autoimmunity; (iv) AR ITCH deficiency: autoimmunity, dysmorphic facial features and neurodevelopmental delay." (PMID 39945219, 2025).